LINC00706 (long independently transcribed non-coding RNA 706)
Gene: Long non-coding RNA gene on chromosome 10 (6,772,271 to 6,779,205, reverse strand). Ensembl gene ENSG00000281186.
Diseases named in the same sentence as LINC00706 in open-access papers:
LINC00706 is named in the same sentence as 1 disease in open-access papers, as found by Europe PMC text mining. Sharing a sentence is not in itself a finding about the gene and the disease. The quoted sentences say what the papers report.
tumours (1 paper, 2023). "We aimed to investigate by means of RT‐qPCR, the expression of DNAH17‐AS1, LINC00706, SLC25A5‐AS1, CADM3‐AS1 and MIR7‐3HG in NFPA samples compared to that in healthy tissues adjacent to the tumours." (PMID 37933082, 2023).